HCN1 (hyperpolarization activated cyclic nucleotide gated potassium channel 1)
Description:
Hyperpolarization-activated ion channel that are permeable to sodium and potassium ions. Displays lower selectivity for K(+) over Na(+) ions. Contributes to the native pacemaker currents in heart (If) and in the generation of the I(h) current which controls neuron excitability. Participates in cerebellar mechanisms of motor learning (By similarity). May mediate responses to sour stimuli (By similarity).
Synonyms: BCNG-1; BCNG1; HAC-2; DEE24; EIEE24; GEFSP10
Tractability: Small molecule: a structure with a bound ligand is known; a high-quality ligand is known; it belongs to a druggable protein family. Antibody: UniProt places it where antibodies can reach, with high confidence; its Gene Ontology location is reachable by antibodies, with high confidence; UniProt predicts a signal peptide or a membrane-spanning region. PROTAC: ubiquitination databases record sites on it; a small molecule that binds it is known.
Target class: Ion channel; Voltage-gated ion channel; Cyclic nucleotide-regulated channel
Chemical probes: RO7293275 (high quality)
Gene: Protein-coding gene on chromosome 5 (45,254,948 to 45,696,498, reverse strand). Ensembl gene ENSG00000164588.
Subcellular location: Cell membrane
Pathways (Reactome):
Neuronal System: HCN channels
Gene Ontology:
Molecular function: cAMP binding; protein binding; voltage-gated monoatomic cation channel activity; voltage-gated potassium channel activity; voltage-gated sodium channel activity; intracellularly cAMP-activated cation channel activity; potassium channel activity; identical protein binding; monoatomic ion channel activity; phosphatidylinositol-3,4,5-trisphosphate binding; phosphatidylinositol-4,5-bisphosphate binding; sodium channel activity
Biological process: cellular response to cAMP; potassium ion transmembrane transport; protein homotetramerization; regulation of membrane depolarization; regulation of membrane potential; sodium ion transmembrane transport; potassium ion import across plasma membrane; regulation of heart rate by cardiac conduction; regulation of SA node cell action potential; sodium ion import across plasma membrane; cellular response to interferon-beta; maternal behavior; monoatomic ion transport; negative regulation of action potential; positive regulation of membrane hyperpolarization; potassium ion transport; regulation of membrane hyperpolarization; regulation of postsynaptic membrane potential; response to calcium ion; response to L-glutamate; transmembrane transport
Cellular component: HCN channel complex; plasma membrane; axon; dendrite; apical dendrite; axon terminus; basolateral plasma membrane; cell surface; dendrite membrane; dendritic shaft; glutamatergic synapse; membrane; neuronal cell body; postsynaptic membrane; presynaptic active zone membrane; somatodendritic compartment
Genetic constraint (gnomAD): Loss-of-function variants: 13 observed, 62.91 expected, observed/expected ratio (o/e) 0.21, 90% interval 0.13 to 0.33. The synonymous counts are far from expectation, so gnomAD's model fits this gene poorly and the ratio says little. Missense variants: 764 observed, 1,053.1 expected, observed/expected ratio (o/e) 0.73, 90% interval 0.68 to 0.77. Synonymous variants: 518 observed, 423.84 expected, observed/expected ratio (o/e) 1.22, 90% interval 1.14 to 1.31.
Gene-disease validity (ClinGen):
ClinGen rates the evidence that HCN1 causes each of these diseases.
generalized epilepsy with febrile seizures plus (autosomal dominant): Definitive. A familial epilepsy syndrome in which family members display a seizure disorder from the generalized epilepsy with febrile seizures plus spectrum which ranges from simple febrile seizures (FS) to the more severe phenotype of myoclonic-astatic epilepsy (MAE) or Dravet syndrome (DS).
Homologues: Orthologues: chimpanzee HCN1 (99% identical), macaque HCN1 (99% identical), pig HCN1 (97% identical), rabbit HCN1 (95% identical), mouse Hcn1 (95% identical), rat Hcn1 (95% identical), dog HCN1 (94% identical), tropical clawed frog hcn1 (79% identical), zebrafish hcn1 (73% identical), guinea pig HCN1 (68% identical), Drosophila melanogaster Cngl (23% identical), Drosophila melanogaster Elk (18% identical), and 9 more. Paralogues in human: HCN4 (62% identical), HCN2 (59% identical), HCN3 (51% identical), KCNH2 (19% identical), KCNH4 (19% identical), KCNH8 (18% identical), KCNH5 (18% identical), KCNH3 (18% identical), CNGA3 (18% identical), KCNH7 (18% identical), KCNH1 (18% identical), CNGB1 (18% identical), and 5 more.
Diseases named in the same sentence as HCN1 in open-access papers:
HCN1 is named in the same sentence as 80 diseases in open-access papers, as found by Europe PMC text mining. Sharing a sentence is not in itself a finding about the gene and the disease. The quoted sentences say what the papers report.
epilepsy (41 papers, 2012 to 2026). A brain disorder characterized by episodes of abnormally increased neuronal discharge resulting in transient episodes of sensory or motor neurological dysfunction, or psychic dysfunction. "Numerous human mutations linked to epilepsy have been identified in the HCN1 gene, with critical mutations potentially leading to early infantile epileptic encephalopathy." (PMID 39307309, 2024). "In conclusion, the present study expands the genotypic and phenotypic spectrum of patients with HCN1-related epilepsy and clarifies the underlying mechanisms." (PMID 35845605, 2022). "To date, a total of 40 different missense variants in the HCN1 gene have been reported in patients affected by epilepsy and/or neurodevelopmental disorders (source: HGMD Professional 2020.4)." (PMID 35972069, 2022). "Here we present a patient harboring a novel de novo HCN1 E246A variant with mild epilepsy and developmental delay." (PMID 35359652, 2022). "With the development of whole-exon sequencing, mutations in HCN1 have been identified as causes of epilepsy." (PMID 35845605, 2022). "In the present study, we reported five new patients with HCN1-related epilepsy and identified four unreported variants." (PMID 35845605, 2022). "Epilepsies caused by de novo HCN1 variants tend to be the severe developmental and epileptic encephalopathies (DEEs), while inherited variants cause milder epilepsy syndromes such as genetic epilepsy with febrile seizures plus (GEFS+)." (PMID 35359652, 2022). "Loss of dendritic HCN1 subunits which resulted in the enhanced cortical excitability and the development of epilepsy." (PMID 35663267, 2022). "When tested in heterologous expression systems, epilepsy-linked HCN1 mutations have been shown to affect the channel in several different ways." (PMID 35972069, 2022). "We identified pathogenic variants of HCN1 (n = 24), HCN2 (n = 8), HCN3 (n = 2), and HCN4 (n = 6) that were associated with epilepsy in 74 cases (43 HCN1, 20 HCN2, 2 HCN3, and 9 HCN4)." (PMID 35663267, 2022). "Why do HCN1 mutations that in heterologous expression systems have divergent effects on channel function equally result in epilepsy, and a similar paradoxical response to certain Na+ channel blockers?" (PMID 35972069, 2022). "Here we describe a child harboring a novel de novo HCN1 variant, E246A, in a child with epilepsy and mild developmental delay." (PMID 35359652, 2022). "Genetic analysis of epilepsy patients revealed that the loss-of-function mutations in the HCN1 gene is responsible for various epilepsies, such as febrile seizures, genetic generalized epilepsies, and neonatal epileptic encephalopathy." (PMID 34149352, 2021). "To date, a number of missense mutations reported in human HCN1 demonstrate that disrupting this channel leads to various forms of epilepsy." (PMID 25142030, 2015). "In a slightly larger study, using exome sequencing in 39 patients with fever-associated epilepsies similar to Dravet syndrome, Nava and colleagues identified two de novo mutations in HCN1." (PMID 26302787, 2015). "Since changes in HCN1 abundance or subcellular localization are associated with learning and memory, epilepsy, and pain, it is important to understand how the trafficking of HCN1 is regulated in various cell types." (PMID 24409334, 2014). "Indeed, the individuals carrying the p.(Met374Leu) HCN2 or the p.(Met305Leu) HCN1 variants have epilepsy and neurodevelopmental disorders." (PMID 40468825, 2025). "Because HCN1 associates with APP and X11 or X11L in the brain, genetic deficiency of X11/X11L may induce aberrant HCN1 distribution along with epilepsy." (PMID 37450922, 2024). "Here we aimed to assess the biophysical properties of the HCN1 E246A variant to see if dysfunction of this gene could underlie both the epilepsy and the unusual clinical finding of poor color discrimination." (PMID 35359652, 2022).
epilepsy (continued). "According to the electrophysiological studies on cell culture models, both GOF and LOF HCN1 variants are associated with epilepsy, but LOF is associated with more severe phenotypes, including 3 deaths due to the deletion and a strong reduction in HCN1 current density." (PMID 35663267, 2022). "Hyperpolarization activated cyclic nucleotide-gated channel 1 (HCN1) is expressed throughout the nervous system and is critical for regulating neuronal excitability, with mutations being associated with multiple forms of epilepsy." (PMID 35679272, 2022). "Therefore, impaired voltage-dependent gating properties of HCN1 channels due to certain variants can allow continuous excitatory cation flow that produces epilepsy." (PMID 35663267, 2022). "It is notable that seizures, particularly for status epilepticus, decrease the expression and suppress the function of HCN1 channels, which may imply worse endings of epilepsy caused by LOF variants." (PMID 35845605, 2022). "Variants of HCN1 have been recognized as causes of epilepsy, and mutant HCN1 channels could act with loss-of-function (LOF), loss- and gain-of-function (LOF and GOF) and gain-of-function (GOF) mechanisms." (PMID 35845605, 2022). "Most rodent models of epilepsy support the fact that the loss of the HCN1 current in pyramidal, cortical, and thalamic neurons is associated with the occurrence of epilepsy, but there is limited evidence showing that the upregulation of this current can produce epilepsy." (PMID 35663267, 2022). "Several of the identified epilepsy-associated HCN1 variants generate channels with what have been deemed ‘gain of aberrant’ function properties, implying that HCN channel blockers may be potentially helpful." (PMID 35972069, 2022). "Highly polarized activated cyclic nucleotide gating (HCN) channels encoded by 4 genes (HCN1-4) have been reported to undergo transcriptional changes in patients with epilepsy, with the possible mechanism of influencing excitability in patients with epilepsy." (PMID 33746751, 2021). "Perturbation of HCN1 underlies some forms of epilepsy and chronic pain." (PMID 25142030, 2015). "Because HCN1 associates with amyloid-β precursor protein (APP) and X11/X11L in the brain, genetic deficiency of X11/X11L may induce aberrant HCN1 distribution along with epilepsy." (PMID 23034178, 2012). "HCN1 is also expressed in astrocytes and microglial cells, and participates in the pathophysiological changes that underlie many diseases, but its physiological functions in these cells and the potential changes in its levels of expression related to epilepsy are yet to be studied." (PMID 37366350, 2023). "In addition to the findings that LOF and GOF HCN1 mutants could cause epilepsy, we unveiled that the HCN1 mutants could exert effects on neurons in different manners." (PMID 35845605, 2022). "Genetic variants in the HCN1, HCN2, and HCN4 have been identified in patients with various forms of epilepsy, including febrile seizures, temporal lobe epilepsy, absence epilepsy, and epileptic encephalopathy." (PMID 39361439, 2024). "HCN1 channels represent a pivotal class of drug targets with significant clinical implications for disorders such as epilepsy, depression, and cognitive impairments." (PMID 39307309, 2024). "HCN channels are composed of four subunits (HCN1‐4), with HCN1, HCN2, and HCN4 previously linked to epilepsy." (PMID 39361439, 2024). "A large number of experiments have demonstrated that the total protein expression of HCN1 is decreased in animal models of epilepsy and epileptic patients." (PMID 37366350, 2023). "Hyperpolarization-activated cyclic nucleotide-gated cation channel 1 (HCN1) is predominantly expressed in neurons from the neocortex and hippocampus, two important regions related to epilepsy." (PMID 37366350, 2023).
epilepsy (continued). "Addressing these issues will help to inspire new strategies to explore the relationship between HCN1 and epileptogenesis, and ultimately promote the development of new targets for epilepsy therapy." (PMID 37366350, 2023). "In this review, we summarize the literature related to HCN1 and epilepsy, aiming to find a possible explanation for this paradox, and explore the correlation between HCN1 and the mechanism of epileptogenesis." (PMID 37366350, 2023). "In conclusion, none of these findings can prove with certainty that selective blocking of HCN1 channels in the brain has a beneficial effect on epilepsy treatment." (PMID 37366350, 2023). "HCN1 is the predominant isoform expressed in the neocortex and hippocampus, which are two important regions related to epilepsy." (PMID 37366350, 2023). "We analyze the alterations in the expression and distribution of HCN1 and the corresponding impact on brain function in epilepsy." (PMID 37366350, 2023). "The changes related to HCN1 in epilepsy also involve a change in the distribution pattern, also known as channel re-localization." (PMID 37366350, 2023). "Both animal models for epilepsy and epileptic patients show decreased HCN1 expression and HCN1-mediated Ih current." (PMID 37366350, 2023). "A large number of studies have demonstrated that the omics-level changes related to the expression and distribution of HCN1 also affect epileptogenesis, progression, and prognosis of epilepsy." (PMID 37366350, 2023). "A particular issue that needs to be considered in future studies that aim to evaluate the effect of increasing HCN1 expression on specific brain areas to treat epilepsy is to finely regulate the amount of HCH1 protein." (PMID 37366350, 2023). "The establishment and maintenance of HCN1 enrichment in the distal end of the dendrites are also regulated in the course of epilepsy." (PMID 37366350, 2023). "Many studies have reported changes in HCN1 expression and distribution in the brain of animal models of epilepsy and in epileptic patients." (PMID 37366350, 2023). "Further testing of these deficits in patients with HCN1 epilepsies is warranted but will be difficult in patients with DEEs who have limited ability to communicate." (PMID 35359652, 2022). "Pathogenic variants of HCN1, HCN2, HCN3, and HCN4 have been reported to be associated with epilepsy in 74 cases, and they have diverse phenotypes." (PMID 35663267, 2022). "Since HCN1 current seems to be essential for the prevention of certain types of epilepsy, there is also the need to develop channel openers." (PMID 35663267, 2022). "In summary, based on the electrophysiological studies on cell models, both GOF and LOF are associated with epilepsy; but LOF is associated with more severe phenotypes, including 3 deaths due to the deletion and strong reduction in HCN1 current density." (PMID 35663267, 2022). "Since HCN1 current is essential for the prevention of epilepsy, there is also the need to develop HCN1 channel openers." (PMID 35663267, 2022). "General information of the HCN1-4 channelopathy in relation to epilepsy based on the available information." (PMID 35663267, 2022). "Gain and loss of function mutations in HCN1 and HCN2 have also been identified in patients with various forms of epilepsy." (PMID 35465092, 2022). "Over the years, more phenotypes of HCN1-related epilepsy have been identified, including severe epilepsy of infancy with migrating focal seizures, absence, and other neurodevelopmental diseases." (PMID 35845605, 2022). "Among these DEGs, Hcn1 was reported to be predominantly expressed in the brain to regulate some brain disorders, such as epilepsy and posttraumatic stress disorders." (PMID 33933147, 2021). "We propose this is part of the tight control imposed on HCN1 trafficking given that altered surface expression of HCN1 is often observed in diseases such as epilepsy." (PMID 25142030, 2015).